BIRC6 (baculoviral IAP repeat containing 6)
Diseases named in the same sentence as BIRC6 in open-access papers (continued):
Sharing a sentence is not in itself a finding about the gene and the disease.
Stroke (1 paper, 2020). Sudden impairment of blood flow to a part of the brain due to occlusion or rupture of an artery to the brain. "This work introduces BIRC6 as a novel genetic risk factor for stroke, and identifies autophagy as a genetically regulated mechanism of carotid plaque vulnerability." (PMID 33317170, 2020).
cancer (49 papers, 2009 to 2025). A tumor composed of atypical neoplastic, often pleomorphic cells that invade other tissues. "Baculoviral IAP repeat containing protein 6 (BIRC6) is one of the apoptosis inhibitor proteins contributing to cancer cells' survival in many cancer types with diagnostic and treatment importance." (PMID 36033570, 2022). "ZHFX3 and BIRC6 can promote the proliferation of tumor cells, meaning that the mutation or knockout of these can inhibit the progression of cancer, resulting in a prolonged OS." (PMID 35087829, 2021). "BIRC6 is associated with cancer in humans, and both cell death and autophagy are highly relevant in cancer biology." (PMID 29929453, 2018). "In particular, increased BIRC6 expression was associated with Gleason 6–8 cancers and castration resistance." (PMID 23409057, 2013). "More than half of the 145 CNAs<2 Mb were mapped to Mendelian CNVs, including GSTT1, glutathione s-transferase and BIRC6, an anti-apoptotic protein, possibly predisposing to some cancers." (PMID 19759907, 2009). "Both BIRC5 and BIRC6 have been linked to cancer in other publications." (PMID 35428183, 2022). "Increased BIRC6 expression was associated with Gleason 6–8 cancers and castration resistance." (PMID 23409057, 2013). "In conclusion, our study highlights elevated levels of AAbs against IFNA and other antigens implicated in various cancers, as well as associations between AAbs targeting LIG3 and BIRC6 with more favorable treatment outcomes." (PMID 40768895, 2025). "Baculoviral inhibitors of apoptotic proteins (BIAPs) repeat-containing protein 6 (BIRC6), is an anti-apoptotic protein that plays an important role in cancers." (PMID 40510224, 2025). "Taken together, the known functions of BIRC6 are integrated into several of the hallmarks of cancer, as proposed by Hanahan." (PMID 41305480, 2025). "BIRC6 is among the apoptosis inhibitors, and prior studies have investigated its role in various cancers, proposing that BIRC6 has the capability to degrade pro-apoptotic proteins and deregulate extrinsic and intrinsic cell death pathways." (PMID 40510224, 2025). "As the different behavior and progression of various cancer types can make a difference in the results of studies, evaluating BIRC6 expression in different cancers, it is necessary to evaluate each tumor type separately." (PMID 40510224, 2025). "Cancer gene analysis of the IS revealed that the IS with the highest retrieval frequency (27% on the spleen of the T4 mouse) was located near BIRC6." (PMID 39062069, 2024). "Previous studies have indicated that the prognostic value of the BIRC6 protein is highly cancer-specific." (PMID 38066801, 2023). "Studies have shown that BIRC6 can regulate the expression of cyclin D1, a vital regulator of the G1 phase of the cell cycle, in cancer cells." (PMID 38066801, 2023). "These dual functions of BIRC6 in both cell death and division make it a promising target for targeted therapy in various types of cancer." (PMID 38066801, 2023). "The role of BIRC6 in many cancer types has been investigated, including the brain, leukemia, osteosarcoma, colon, and lung." (PMID 36033570, 2022). "In addition to the most-commonly altered COSMIC Tier 1 genes, there is a long tail of both cancer-associated and other mutated genes that may play a role in urothelial carcinogenesis and require further investigation; examples include BIRC6, the catalytic arg-200 of GNA13, and Q383H in AHR." (PMID 35655252, 2022). "BIRC6 increases cancer invasion to different tissues, disease recurrence, resistance to different treatments such as chemotherapy, and severity." (PMID 36033570, 2022). "Unlike BIRC5 and BIRC7 which demonstrated a strong oncogenic role, BIRC6 tended to function as a tumor suppressor since it was down-regulated in eight human cancers." (PMID 31964418, 2020).
cancer (continued). "The frequency of apoptosis pathway regulations varied among different IAPs, with BIRC3 and BIRC6 both regulating 36.4% of cancers while BIRC7 only regulating 12.5% of cancers in at least one of the apoptosis pathways (overall proportion test P = 0.0022)." (PMID 31964418, 2020). "The strongest coherence was observed between XIAP and BIRC6 which were clustered together in 97% of the cancers." (PMID 31964418, 2020). "The capacity of apoptosis regulations among IAPs also differed with BIRC3 and BIRC6 both regulating 36.4% of cancers while BIRC7 only regulating 12.5% of cancers in at least one of the apoptosis pathways." (PMID 31964418, 2020). "Increased levels of BIRC6 have been observed in a number of human cancers and shown to correlate with poor prognostic profiles and higher incidences of disease relapse." (PMID 28520795, 2017). "Despite increased interest in BIRC6 and its role in cancer cell survival, its regulation and involvement in mediating drug resistance is not well understood." (PMID 28520795, 2017). "While there is considerable evidence supporting BIRC6’s role in mediating drug resistance in several human cancers, the mechanisms regulating its expression and stability are not well understood." (PMID 28520795, 2017). "Elevated expression of BIRC6 has been found in a variety of cancers, i.e. childhood de novo acute myeloid leukemia, colorectal cancer, neuroblastoma, melanoma and non-small cell lung cancer." (PMID 25071009, 2014). "Accordingly, dual targeting of BIRC6 and cIAP1 or survivin would more effectively induce cancer cell death through acting simultaneously on mutually exclusive pathways." (PMID 25071009, 2014). "The dual roles of BIRC6 in cell death and division processes resemble those of survivin, and render it a promising target for therapy of a variety of cancers." (PMID 25071009, 2014). "Clinical prostate tissue sections, morphologically categorized into benign tissue and cancers of Gleason score 6–8 and 9–10, were stained and scored for BIRC6 expression." (PMID 23409057, 2013). "The results are consistent with reports of a critical role for BIRC6 in the survival of a variety of cancer cells." (PMID 23409057, 2013). "In the Gleason scored tissues, expression of BIRC6 was low for benign tissues and rose steadily, peaking in Gleason score 7 cancers." (PMID 23409057, 2013). "BIRC6 is a member of the Inhibitors of Apoptosis Protein (IAP) family which is thought to protect a variety of cancer cells from apoptosis." (PMID 23409057, 2013). "BIRC6 has been related to the development and progression of different types of cancer in humans." (PMID 41305480, 2025). "As in addition to the classical NAB2-STAT6 fusion, we report four coding variants in cancer-associated genes (BIRC6, KIT, POLQ, and RBM10) which have not been previously reported in SFTs." (PMID 37469410, 2023). "BIRC6 expression has been suggested by many researchers to be correlated with tumor stage and differentiation, angiogenesis, chemotherapeutic response, and other clinical properties in the context of cancer." (PMID 38066801, 2023). "Collectively, these data indicate that BIRC6 might play a conserved role in regulating Hippo pathway in human cancers." (PMID 37699871, 2023). "Additionally, BIRC6 is believed to play an important role in the progression and chemoresistance of several cancers 25-27." (PMID 37781078, 2023). "Moreover, we also observed strong positive correlations between the mRNA of BIRC6 and multiple Hippo pathway target genes across human cancers." (PMID 37699871, 2023). "It showed that the BIRC6 serum level did not have any significant association with age, sex, tumor size, differentiation, metastasis, lymph node involvement, and site of cancer." (PMID 36033570, 2022).
cancer (continued). "For example, BIRC2 was clustered with BIRC3, XIAP and BIRC6 in more than 50% of the cancers." (PMID 31964418, 2020). "Thereby, understanding more detailed molecular mechanisms of how BIRC6 regulates cell death and autophagy may contribute to the development of therapies against cancer in the future." (PMID 29929453, 2018). "BIRC6 has been implicated in drug resistance in several different human cancers, however mechanisms regulating BIRC6 have not been extensively explored." (PMID 28520795, 2017). "In summary, these studies suggest BIRC6 may be a promising target for the treatment of some drug resistant human cancers." (PMID 28520795, 2017). "Thus, BIRC6 mediates resistance to multiple anti-cancer drugs including targeted inhibitors and cytotoxic compounds." (PMID 28520795, 2017). "A large amount of evidence showed that BIRC6 was highly expressed in several types of cancer." (PMID 25933218, 2015). "Nevertheless, the elevation of BIRC6 in castration-resistant cancers suggests that the protein may provide a potential therapeutic target for the disease." (PMID 23409057, 2013). "BIRC6 has been reported to play a significant role in apoptosis resistance of a variety of cancers." (PMID 23409057, 2013). "Furthermore, knocking-down BIRC6 led to growth inhibition in several cancer cell lines and xenografted mice and rendered the tumor cells more sensitive to 5-fluoruracil treatment in vivo and in vitro." (PMID 23211188, 2012). "Low expression of the anti-apoptotic IAP BIRC6 in AML may seem controversial given the often high expression of IAPs in cancer." (PMID 23211188, 2012). "Baculoviral IAP repeat containing protein 6 (BIRC6) is one of the apoptosis inhibitor proteins, which shows its inhibitory function by binding with preapoptosis factors and leading to an apoptosis inhibitory effect; therefore, it contributes to the survival of cancer cells of many cancer types." (PMID 36033570, 2022). "In addition to common treatment modalities such as surgery, chemotherapy, and radiation, one of the recommended ways to control the cancer severity and metastasis and prevent lymph node involvement is to control the expression of various genes and proteins such as BIRC6." (PMID 36033570, 2022). "Our findings of high BIRC6 expression in granulocytes versus AML may reflect the cellular differentiation status of these cells rather than a cancer-associated deregulation." (PMID 23211188, 2012). "The BIRC6 gene was found to express the largest number of circRNAs in GBC samples, which has also been observed in other cancer types." (PMID 39428382, 2024). "Our findings demonstrated that the final score of BIRC6 expression in OLP was significantly lower than in OLPD and malignancies." (PMID 38066801, 2023). "The analysis revealed that several members of the IAP family, including NAIP, BIRC2, BIRC3, XIAP, BIRC5, BIRC6, and BIRC7, exhibited higher expression levels in multiple cancers, including HCC." (PMID 37781078, 2023). "We identified 35 genes that were more frequently altered in HS/CB tumors versus corresponding TCGA cohorts; of which, 8 genes (PREX2, BIRC6, CNTNAP2, PTPRB, GRM3, ANKRD11, BRCA2, and TET3) are listed on the OncoKB Cancer Genes catalogue." (PMID 34446728, 2021). "In particular, BIRC6 and XIAP were positively correlated with REST expression across all cancer types except XIAP in PCPG." (PMID 31964418, 2020).
cancer (continued). "In the present study, we show that BIRC6-knockdown rendered MYL-R cells several-fold more sensitive to imatinib and gemcitabine, two compounds used in cancer therapy." (PMID 28520795, 2017). "Consistent with BIRC6’s role as a putative oncogene, we observe strong enrichment of Hippo signature genes in LAML patients and reveal intensively strong correlations between BRIC6 mRNA and Hippo pathway target genes across numerous cancer types." (PMID 37699871, 2023). "There were not any significant relationships between BIRC6 serum levels and clinical characteristics of the stage, tumor size, metastasis, and site of cancer." (PMID 36033570, 2022). "Up regulation of several IAPs like NAIP (BIRC1), X-linked IAP (XIAP, BIRC4), Survivin (BIRC5), c-IAP1 (BIRC2), c-IAP2 (BIRC3), Apollon (BRUCE, BIRC6), Livin/MLIAP (BIRC7) and IAP-like protein 2 (BIRC8) have been reported in several cancer cells as well as in serum from cancer patients." (PMID 29464049, 2018). "Sections containing both benign tissue and cancer tissue (Gleason grade 3) showed strong positive BIRC6 staining in the malignant epithelium and absent or weak expression in the benign epithelium (data not shown)." (PMID 23409057, 2013). "Although TTC27 is absent in three cancer gene databases, the breakpoints disrupt MSigDB and COSMIC CGC genes BIRC6 and LTBP1, resulting in a LTBP1-BIRC6 gene fusion of unclear effect." (PMID 38947031, 2024). "Although there are currently no direct inhibitors of BIRC6, targeting Lyn or kinases that maintain BIRC6 expression or stability may have therapeutic potential in treating drug resistant CML or other cancers." (PMID 28520795, 2017).
tumor (27 papers, 2008 to 2026). "The dASO-reduced tumor growth was associated with a significant decrease in intratumoral BIRC6 protein expression in both treatment groups compared to the MM control (p = 0.026 for 6w2, p = 0.006 for 6w5)." (PMID 25071009, 2014). "In most of these cases, BIRC6 expression has been shown to correlate with carcinogenesis, tumor progression and poor patient prognosis, as it has been demonstrated to enhance chemoresistance." (PMID 41305480, 2025). "In most of these cases, BIRC6 expression has been shown to correlate with carcinogenesis, tumor progression and poor patient prognosis and has been shown to enhance chemoresistance." (PMID 41305480, 2025). "The results indicated that NAIP, BIRC2, BIRC3, XIAP, BIRC5, and BIRC6 showed significantly higher expression levels in tumor tissues than in normal tissues." (PMID 37781078, 2023). "The current study also detected BIRC6 expression in the cytoplasm of tumor cells, confirming previous studies showing that it is localized to the Golgi compartment and the vesicular system." (PMID 38066801, 2023). "The levels of NAIP, BIRC2, XIAP, and BIRC6 were significantly elevated in the subgroups of tumor stages 1-3 compared to their levels in the normal subgroups, with no discernible differences in their levels in the subgroup of tumor stage 4." (PMID 37781078, 2023). "Third, although our results showed a possible regulation of NFYC-AS1 on BIRC6 and BIRC6 expression indeed increased in tumor tissues, the direct evidence of this regulation still needs to be further discovered." (PMID 36105077, 2022). "Compared to the NCI60 analysis, we further revealed distinct expression pattern of BIRC5 and BIRC7 and synchronized expression for NAIP, BIRC2, BIRC3, XIAP and BIRC6 in multiple tumor types." (PMID 31964418, 2020). "Moreover, when analyzing tumor sections from both experimental models, a marked decrease in the tumor viable area (VA) and an increase in the necrotic area (NA) were observed in those animals treated with the baculovirus capable of silencing BIRC6." (PMID 41305480, 2025). "In particular, BIRC6 overexpression has been found in several tumor tissues." (PMID 41305480, 2025). "Moreover, BIRC6 contributes to malignant progression by conferring resistance to chemotherapy, positioning it as a promising therapeutic target to sensitize tumor cells and improve treatment options." (PMID 41305480, 2025). "So, BIRC6 can be suggested as a marker contributing to tumor surveillance and progression." (PMID 38066801, 2023). "Accordingly, these results may approve the higher expression of BIRC6 in tumor cells with a basal-like phenotype." (PMID 38066801, 2023). "More importantly, we performed in vivo tumor xenograft experiment in nude mice and found that the knockdown of NFYC-AS1 did exhibit the inhibitory effect on tumor growth, whereas the overexpression of BIRC6 could restore the tumor growth in nude mice." (PMID 36105077, 2022). "Increased BIRC6 protein level may be a predictive factor for chemoresistance and an adverse prognostic marker for NSCLC, and inhibiting BIRC6 may be a useful method for treating the tumor." (PMID 31885751, 2019). "However, BIRC6 expression positively correlated with tumor size (P = 0.044) and invasion depth (T stage) (P = 0.013)." (PMID 25933218, 2015). "BIRC6 overexpression was correlated with tumor size and invasion depth of CRC." (PMID 25933218, 2015). "Interestingly, combination of BIRC6 knockdown and CDDP treatment significantly inhibited the tumor growth compared with either BIRC6 knockdown or CDDP treatment alone." (PMID 25933218, 2015). "BIRC6 is up-regulated in tumours and inhibits active caspase 3 through binding with its BIR domain." (PMID 26115916, 2015). "Second, tumor cells with both BIRC6 and cIAP1/survivin silenced could have underwent apoptosis during the early phase of treatment, thus, silenced cells were not captured in the current detection window." (PMID 25071009, 2014).
tumor (continued). "BIRC6 was selected for further analysis as a tumor driving gene." (PMID 22788920, 2012). "Additionally, several mutations not previously reported in OSCC sequencing studies were detected in 7% of cases including mutations in ARID1A (chromatin remodeling), BIRC6 (apoptosis inhibition), DCC (neural regulation and tumor suppression), and NCOR1 (transcriptional inhibition)." (PMID 41154345, 2025). "Thus, variations in BIRC6 play a role in tumorigenesis that may be related to diverse genetic defects that affect BIRC6 expression in unique tumor types." (PMID 38066801, 2023). "More importantly, IHC of BIRC6 from 34 LUAD patients showed significantly lower expression in NFYC-AS1 low or normal lung tissues and a markedly elevated expression in tumor tissues with high NFYC-AS1 expression." (PMID 36105077, 2022). "We observed that the BIRC2, BIRC3, BIRC5, and BIRC7 genes showed the increased levels of expression in tumor tissue compared to normal tissue, while in the case of the BIRC1, BIRC4, BIRC6, and BIRC8 genes, we saw the decreased expression levels." (PMID 33673050, 2021). "ZHFX3, BIRC6, Axin2, CPEB3 and TPR can regulate the proliferation and apoptosis of tumor cells." (PMID 35087829, 2021).